LBP (lipopolysaccharide binding protein)
Diseases named in the same sentence as LBP in open-access papers (continued):
Sharing a sentence is not in itself a finding about the gene and the disease.
depression (9 papers, 2020 to 2025). "In a human study, higher levels of LPS were related to more severe depressive symptoms, and serum levels of LPS-binding protein (LBP), which binds to LPS and facilitates its detection by the host’s immune system, have been associated with elevated depression scores." (PMID 38476949, 2024). "Blood-based biomarkers of intestinal permeability such as zonulin, I-FABP, LPS, LBP, and sCD14 have shown altered levels in patients with depression, although findings remain inconsistent." (PMID 41155365, 2025). "Our results highlighted a correlation between depression and calprotectin and LBP, which contributes another step to the rapid identification of biomarkers and can indicate the existence of depression." (PMID 36079050, 2022). "Therefore, it is possible that the lack of typical depression-like behavior in the UCMS rats was because the inflammation profile as assessed by the LBP, and cytokine levels did not cause alteration to the kynurenine pathway." (PMID 37512945, 2023). "Fang’s team suggested that during lipopolysaccharide (LPS)-induced depression, LPS inhibited the activity and expression of AADC by increasing plasma lipopolysaccharide-binding protein (LBP), ultimately leading to depressive-like phenotypes." (PMID 40342516, 2025). "The aim of the present study was to investigate the role of intestinal permeability biomarkers, i.e., calprotectin, zonulin, lipopolysaccharide-binding protein (LBP) and intestinal fatty acid-binding protein (I-FAB), in relation to depression in patients with inflammatory bowel disease (IBD)." (PMID 36079050, 2022). "This is the first study in Romania, Eastern Europe, to include the set of biomarkers of intestinal permeability, i.e., calprotectin, zonulin, LBP and IFABP/FABP2, in the study of depression in patients with IBD for analysing whether intestinal permeability syndrome is correlated with depression." (PMID 36079050, 2022).
systemic inflammatory response syndrome (9 papers, 2006 to 2026). SIRS is a serious condition related to systemic inflammation, organ dysfunction, and organ failure. "Regardless of these observations, the change in both IFABP and LBP is far below thresholds thought to be clinically meaningful in the sense of downstream inflammation and systemic inflammatory response syndrome." (PMID 40542541, 2025). "In this study, we examined the role of LBP in pathogenesis of LPS induced systemic inflammatory response syndrome (SIRS)." (PMID 23437199, 2013).
pneumonia (8 papers, 2012 to 2025). An acute, acute and chronic, or chronic inflammation focally or diffusely affecting the lung parenchyma, caused by an infection in one or both of the lungs (by bacteria, viruses, fungi, or mycoplasma.). "CD14-dependent pathways, potentially related to LPS, LBP, and sCD14 concentrations, have been implicated in pneumonia-related inflammation in ARDS." (PMID 40375981, 2025). "Six different laboratory tests (white blood cell count (WBC), erythrocyte sedimentation rate (ESR), C-reactive protein (CRP), procalcitonin (PCT), lipopolysaccharide binding protein (LBP) and fibrinogen were used to examine the diagnostic value of radiographic pneumonia." (PMID 31110214, 2019). "The optimal cut-off concentrations that showed the highest prognostic accuracy (highest sensitivity and specificity) for IL-6, LBP and IL-10 in predicting a severe course of pneumonia were calculated using data from the ROC analyses." (PMID 22348735, 2012). "In patients with a severe course of pneumonia, we found significantly increased IL-6 and LBP concentrations." (PMID 22348735, 2012). "Median LBP levels in patients with pneumonia caused by Gram-negative organisms were significantly lower (18.10 ± 11.76 μg/ml) compared with patients with pneumonia caused by Gram-positive bacteria (28.40 ± 25.38 μg/ml; P < 0.001)." (PMID 22348735, 2012). "ROC curves illustrate the accuracy of IL-6, LBP and IL-10 concentrations, and CRB-65 and CRB scores, in predicting a severe course of pneumonia." (PMID 22348735, 2012). "Among these, LBP, IL-6, and IL-2R are features for CAP diagnosis, and the combination of LBP, sFas, TRAIL, IL-6, and IL-8 allowed discrimination between uncomplicated and severe forms of pneumonia." (PMID 37342494, 2023).
schizophrenia (8 papers, 2018 to 2025). A major psychotic disorder characterized by abnormalities in the perception or expression of reality. "This breach facilitates bacterial translocation, as evidenced by the significant increase in markers such as soluble CD14 and LBP in the blood of individuals with schizophrenia." (PMID 41346597, 2025). "We report evidence of increased levels of intestinal permeability biomarkers, specifically LBP and LPS, in patients with schizophrenia." (PMID 39676547, 2024). "Results revealed elevated levels of LBP and LPS in a significant proportion of patients with schizophrenia (62% and 25.6%, respectively)." (PMID 39676547, 2024). "The objective of this article was to evaluate the intestinal integrity of patients with schizophrenia, by analyzing plasma biomarkers of intestinal permeability or bacterial translocation: LBP, LPS, and I-FABP." (PMID 39676547, 2024). "They found that soluble CD14 was more prevalent in patients with schizophrenia and both sCD14 and LBP correlated with CRP in that group." (PMID 30374300, 2018). "Data from this meta-analysis of increased blood levels of alpha-1-antitrypsin, lipopolysaccharide-binding protein (LBP), soluble CD14 (sCD14) also suggest an increase in intestinal permeability in schizophrenia." (PMID 35546942, 2022). "Among these, a negative correlation was observed between plasma lipopolysaccharide-binding protein (LBP) levels and C4A gene copy number was observed in patients with schizophrenia, but not in healthy controls." (PMID 41346597, 2025). "The apparent LBP elevation was not schizophrenia‐specific; its strong correlations with CRP and neutrophils point to smoking related inflammation rather than a schizophrenia specific effect." (PMID 41084047, 2025).
breast cancer (7 papers, 2010 to 2025). A primary or metastatic malignant neoplasm involving the breast. "The RBP4/RhoA/Rock1 axis has been found to regulate the proliferation, migration, and invasion of ovarian cancer cells, while NRG2 was identified as a prognostic marker for GC and breast cancer and LBP as a prognostic marker for GC." (PMID 40406134, 2025). "Our current study showed that breast cancer patients who received neoadjuvant chemotherapy showed higher plasma levels of lipopolysaccharide-binding protein as an indicator of circulating proinflammatory LPS levels compared to treatment-naïve patients." (PMID 36230772, 2022). "We measured the LPS binding protein (LBP) concentration in plasma samples obtained from breast cancer patients, either before systemic adjuvant treatment or after receiving neoadjuvant chemotherapy." (PMID 36230772, 2022). "Serum LBP was higher in Tumor mice relative to Control, but attenuated in the Resected group, further supporting disruption of the intestinal barrier due to mammary tumor implantation." (PMID 35248004, 2022). "Other interesting candidates include CXCR4, a receptor implicated in mediating metastasis of breast cancer cells through its ligand SDF-1, and CD14 and lipopolysaccharide-binding protein (LBP), which are implicated in Toll-like receptor signaling and LPS-mediated inhibition." (PMID 20346151, 2010). "LBP is mainly expressed in hepatocytes, producing lipopolysaccharide-binding protein, which plays an important role in innate immunity, and its relationship with melanoma has not been explored, and its position in osteosarcoma, lung cancer and breast cancer has been marked as protective." (PMID 37666853, 2023). "The levels of Lipopolysaccharide-binding protein (LBP) and soluble CD14 (sCD14) serve as markers for bacterial translocation, indicating the potential existence of a gut-breast cancer microbiota axis." (PMID 38521934, 2024). "More recently, we have shown that Lipopolysaccharide-Binding Protein (LBP) levels correlate with dose-volume histogram (DVH) parameters and diastolic cardiac function in patients treated for breast cancer using RT." (PMID 37274244, 2023).
co-infection (7 papers, 2015 to 2025). "Moreover, P. fragile co-infection elevated the levels of plasma indicators of gastrointestinal barrier permeability (intestinal fatty acid-binding protein) and microbial translocation (lipopolysaccharide binding protein and sCD14)." (PMID 40950582, 2025). "Based on the microarray data, TLR4 and LBP were slightly but markedly upregulated (1.79- and 1.8-fold, respectively) in the H1N1-SS2 co-infection group." (PMID 25906258, 2015). "Elevated levels of LBP were present in patients with HIV and HIV/HCV co-infection and were reduced by ART." (PMID 25785448, 2015). "We hypothesized that the levels of microbial products (as measured by LPS) and inflammatory response to microbial products (sCD14, LBP) are altered and elevated in patients with chronic HIV/HCV co-infection." (PMID 25785448, 2015).
gram-negative bacterial infections (7 papers, 2011 to 2024). Infections caused by bacteria that show up as pink (negative) when treated by the gram-staining method. "Lipopolysaccharide-binding protein (LBP) is a 60 k Da molecular protein that belongs to type I reactive proteins and is produced during the acute phase of gram-negative bacterial infections in the peripheral blood." (PMID 39274240, 2024). "LBP has been reported as an essential component of the innate immune responses to gram-negative bacterial infection and can protect murine liver from different injuries." (PMID 30422989, 2018). "LBP/BPIs are structurally related proteins belonging to the lipid transfer/binding protein (LT/LBP) family, which represent important components of the innate immune system against Gram-negative bacterial infections." (PMID 24367257, 2013).
liver cirrhosis (7 papers, 2010 to 2025). "Here, we investigated the association between BsmI, ApaI, TaqI and FokI VDR polymorphisms and the severity of liver cirrhosis in relation to serum cytokine and lipopolysaccharide binding protein (LBP) levels and their role on survival in cirrhotic patients." (PMID 30218108, 2018). "In patients with liver cirrhosis, plasma LBP was also positively correlated with procalcitonin (r = 0.480, p = 0.004) and CRP (r = 0.703, p < 0.001) but not with IL-6 and immune cell numbers." (PMID 39997462, 2025). "Serum LBP levels were significantly elevated in both chronic hepatitis and liver cirrhosis groups compared to healthy controls (p < 0.001, p < 0.01, respectively)." (PMID 36035413, 2022). "Whether plasma LBP levels in critically ill patients with liver cirrhosis are similarly reduced as CRP or change in patients with underlying pancreatitis needs to be evaluated." (PMID 39997462, 2025). "Comparison of male with female patients without liver cirrhosis (p = 0.373) and male with female patients with liver cirrhosis (p = 0.687) revealed similar levels of plasma LBP." (PMID 39997462, 2025). "Because of the low plasma LBP levels of patients with liver cirrhosis, these patients were not included in the further analyses." (PMID 39997462, 2025). "Concentrations of LBP were similar in HIV-infected patients with or without HCV coinfection (with or without liver cirrhosis) (p>0,05)." (PMID 25775475, 2015). "Median serum LBP levels were not statistically different between patients with liver cirrhosis and healthy subjects (21, 860 vs. 19, 333 ng/ml, p = 0.08)." (PMID 20886039, 2010). "LBP, which is abundant in hepatocytes, is increased in non-septic patients with liver cirrhosis." (PMID 39997462, 2025).
periodontitis (7 papers, 2015 to 2024). An acute or chronic inflammatory process that affects the tissues that surround and support the teeth. "CRP, elastase, lipopolysaccharide binding protein, and IL-6 levels were elevated in patients with untreated aggressive periodontitis compared to healthy control group." (PMID 26346216, 2015). "Furthermore, hepatocytes are responsible for the production of LBP which blood levels are increased in chronic and aggressive periodontitis." (PMID 33746772, 2021). "In our study, LBP and HGF exhibited more than ~ 5 × higher concentration levels in periodontitis than in health groups, in line with the literature." (PMID 33742017, 2021). "For discriminating health vs periodontitis groups, the predictor variables resulting from the CART analysis included HGF, MMP-9, LBP and IL-1b." (PMID 33742017, 2021). "In different sites from the same periodontitis patients (P2: P3, P7: P8, and P9: P10), it was clearly noticeable that MMP3, MMP13, and LBP expressions differ in a site-specific manner." (PMID 27531006, 2016).
viral infection (7 papers, 2014 to 2025). "Here, LBP levels in a viral infection were also higher in patients with dengue infection than in controls but were not different between patients with severe and nonsevere dengue infection (t = 0)." (PMID 34835514, 2021). "Our results further confirmed the relationship between virus infection and LBP expression found in TCGA and GEO datasets." (PMID 32793465, 2020). "As LPS levels increase during advanced viral infection even though they are highly variable, we were able to confirm the extent of MT by determining the plasma LBP concentration." (PMID 25759828, 2014). "This correlation aligns with the concept that LBP might be involved in regulating compensatory anti-inflammatory responses during acute viral infections." (PMID 40565820, 2025). "Therefore, our preliminary data indicate that LBP may be another key element by which virus infection leads to the development and progression of HBV-related HCC." (PMID 32793465, 2020). "Therefore, our results further confirmed the relationship between virus infection and LBP expression found in the TCGA and GEO datasets, which suggested that gene expression of LBP was significantly associated with poor overall survival in patients with hepatitis virus infection." (PMID 32793465, 2020). "Increased LBP-levels have been reported in the BALF of pigs after viral infection and it was shown in vitro that pneumocytes of type II are capable of producing LBP, all supporting the hypothesis, that LBP can be produced in the lung as a local reaction to the inoculation with C. psittaci." (PMID 26209015, 2015). "Pairwise analysis compared to YWOH revealed significant differences by virus infection between YWH and YWOH in at least four immune markers, including intestinal barrier dysfunction markers LBP and iFABP, macrophage activation marker sCD14, and inflammatory chemokine IL-8." (PMID 40862746, 2025). "This further supports the notion that LBP levels may not reflect nutritional status in acute viral infections." (PMID 40565820, 2025).
inflammatory bowel disease (6 papers, 2008 to 2024). A spectrum of small and large bowel inflammatory diseases of unknown etiology. "In mice, it has been demonstrated that sCD14 presents protective effects in inflammatory bowel disease and that a rise in the LBP/sCD14 ratio in both humans and mice is linked to an increase in plasma IL-6." (PMID 38202282, 2024). "LPS and LBP have been used as clinical markers of MT in several disease settings, such as inflammatory bowel disease, HIV-1, and SIV infection." (PMID 25759828, 2014).
ischemic stroke (6 papers, 2019 to 2025). A stroke disorder caused by obstruction of blood flow to the brain, due to thrombotic (local blood clot formation) or embolic (due to a blood clot or other material traveling from another site) event. "This likely explains the correlation of LPS levels with LBP levels with ischemic stroke, TIA, and ICH in the current study." (PMID 33753837, 2021). "Compared to healthy controls, higher LBP and sCD14 concentrations have been observed in patients with ischaemic stroke, especially in those with a poor short-term prognosis." (PMID 32084157, 2020). "Plasma LPS and LBP associate with major causes of ischemic stroke and with ICH, whereas LPS/LBP do not associate with TIAs." (PMID 33753837, 2021). "Thus, this study assessed plasma levels of LPS, LBP, LTA, and CRP in patients with different causes of ischemic stroke, intracerebral hemorrhage (ICH) and transient ischemic attacks (TIAs) compared to controls." (PMID 33753837, 2021). "Since there might be some concern about LPS contamination, these findings were supported by elevated LPS-binding protein (LBP) levels in ischemic stroke (CE and LAA) and ICH compared to controls." (PMID 33753837, 2021). "The rising blood levels of LBP and sCD14 may serve as a compensatory mechanism to prevent excessive TLR4 stimulation and to limit systemic inflammation in patients with ischemic stroke." (PMID 39859200, 2025). "The LPS-NC, LPS-binding protein (LBP), soluble CD14 (sCD14), lipoprotein profiles, apo(lipoprotein) A-I, apoB, and phospholipid transfer protein (PLTP) activity, were determined in 98 ischemic stroke patients and 100 age- and sex-matched controls." (PMID 32084157, 2020). "Six candidate proteins (LBP, VCAM1, FCN2, FBLN1, APOC-I, and APOB) were assessed using individual samples from the CAD and non-CAD ischemic stroke subjects." (PMID 32508734, 2020). "For the first time, differential expressions of apolipoprotein B, apolipoprotein C-I, lipopolysaccharide-binding protein, vascular cell adhesion molecule 1, fibulin-1, and ficolin-2 were confirmed as being significantly upregulated in CAD as compared to non-CAD ischemic stroke subjects." (PMID 32508734, 2020).
lung carcinoma (6 papers, 2014 to 2023). "This analysis resulted in 4 novel miR-21 putative target genes; solute carrier family 5 (iodide transporter) member 8 (Slc5a8), lipopolysaccharide binding protein (Lbp), V-myc myelocytomatosis viral oncogene homolog 1, lung carcinoma derived (Mycl1), PDZ and LIM domain 3 (Pdlim3)." (PMID 24497923, 2014). "Furthermore, we only revealed a preliminary correlation among lung cancer intestinal microbiota, metabolites, and proteomics, but the causal relationship among P. copri‐nervonic acid and all‐trans‐retinoic acid‐CRP, LBP, and CD14 axis needs further investigations." (PMID 35735103, 2022). "FGFR3, LBP, LECT2, and DYNC1I1 were distinguishable markers in lung cancer." (PMID 32528533, 2020). "To evaluate the translational value of our findings, we measured serum LBP and IL-6 levels in a cohort of 152 patients suffering from colorectal or lung cancer accompanied or not by cachexia." (PMID 29719601, 2018). "In line with this altered gut barrier function, LBP and IL-6 levels were increased in cancer cachectic patients versus cancer non-cachectic patients in two populations of patients (lung cancer and colorectal cancer)." (PMID 29719601, 2018).